ERBB4 (erb-b2 receptor tyrosine kinase 4)
Diseases named in the same sentence as ERBB4 in open-access papers (continued):
Sharing a sentence is not in itself a finding about the gene and the disease.
cancer (continued). "When the ERBB4 promoter region SNP status was compared with clinicopathological characteristics, the −782G>T variant was associated with well-differentiated cancer (P = 0.018)." (PMID 25036186, 2014). "ERBB4 activation markedly activated Rac1, which has well-established links to cytoskeletal dynamics and cell migration, and which is implicated in cancer cell invasion and metastasis." (PMID 23681745, 2013). "GWAS studies have also associated ERBB4 variants with polycystic ovary disease and human cancers." (PMID 37855863, 2024). "Since EGF can bind to receptors other than EGFR, such as ErbB2 (HER2), ErbB3 (HER3), and ErbB4 (HER4) across most cancer contexts, and is a key player in cancer metastasis, it is likely that the EGF-associated mechanisms driving EMT are distinct from those regulating MHC I expression." (PMID 38067396, 2023). "We also found mostly concordance concerning the ERBB4 mutation between both primary PCa samples and matched lymph node metastasis, underlining that the identification of alterations in the primary tumor is extremely important for cancer prognosis prediction." (PMID 36077746, 2022). "ERBB4 is a member of the ERBB family of oncogenes that is frequently mutated in different cancer types but the functional impact of its somatic mutations remains unknown." (PMID 36860695, 2022). "Interestingly, the COSMIC, cBioPortal, and AACR GENIE cancer registries include several other examples of glutamate-to-lysine mutations at residues analogous to ERBB4 E715/E934 within the ERBB family genes." (PMID 36860695, 2022). "The mutation of ERBB4 led to a higher TMB level in various cancers (p < 0.0001)." (PMID 34620079, 2021). "In particular, some cancer-associated mutations of ErbB4 can promote loss of ErbB4 kinase activity as these alterations weaken the important functional interactions in the catalytic core and may interfere with the protein stability." (PMID 31245384, 2019). "As mentioned in the introduction, ERBB4 mutations have been linked to different cancer types." (PMID 29342193, 2018). "Of note, a cancer-associated mutation of ERBB4 has been described in TC71 cells." (PMID 27374103, 2016). "ERBB4 is one of the top 127 significantly mutated genes across 12 cancers." (PMID 25516216, 2014). "Inappropriate signaling through the epidermal growth factor receptor family (EGFR1/ERBB1, ERBB2/HER2, ERBB3/HER3, and ERBB4/HER4) of receptor tyrosine kinases leads to unregulated activation of multiple downstream signaling pathways that are linked to cancer formation and progression." (PMID 25386657, 2014). "The results indicate that the ERBB4 variant −815A>T was significantly associated with poor distant disease-free survival, indicating for the first time a possible prognostic significance for a genetic variant of ERBB4 in cancer." (PMID 25036186, 2014). "This is the first indication of prognostic significance for a genetic variant of ERBB4 in cancer." (PMID 25036186, 2014). "Because many receptor proteins (e.g., EGFR, PDGFRA, PDGFRB, ERBB2, and ERBB4) are typically located in the upstream of cancer-related signaling pathways such as proliferation, cell death, and cell cycle progression, mutations in these genes are likely critical to cancer development." (PMID 24516372, 2014). "VAV3 facilitates ERBB4-mediated cancer cell migration, linking growth factor signaling to enhanced motility and invasion." (PMID 41516402, 2026). "In the MI group, we detected significant interactions between macro-C3-SPP1 and MHC-II+ cancer cells via the EREG/ERBB4 axis, which activates downstream MEK/ERK and PI3K/AKT signalling pathways, promoting cell proliferation and survival." (PMID 41281745, 2025). "The ERBB signaling pathway, mediated by ERBB receptor tyrosine kinases (ERBB-1/EGFR, ERBB-2/HER2, ERBB-3, and ERBB-4), is crucial for cellular proliferation, survival, migration, and angiogenesis, which leads to cancer progression." (PMID 40901642, 2025).
cancer (continued). "The ERBB4 gene in “Proteoglycan in Cancer”, the AR gene in “Pathways in Cancer” and “Estrogen Response Early” pathways, were upregulated in the transition from ovarian epithelial cells to LGSC." (PMID 38534733, 2024). "Taken together, these findings implicate a potential role for ERBB4 in GR longevity and provide evidence that within-breed canine lifespan studies could serve as a mechanism to identify favorable or disease-modifying variants important to the axis of aging and cancer." (PMID 37855863, 2024). "ErbB4’s role extends beyond oncology into neurological development, making it a subject of interest in both cancer therapy and neurobiology." (PMID 39138146, 2024). "Overall, we demonstrate that EGFR, ERBB2 and ERBB4 fusions are present across numerous cancer types and importantly are excellent candidates for targeted therapy development." (PMID 37168365, 2023). "In our study, several GP extract-upregulated genes, such as ERBB4 and GL1, are associated with diverse cancers." (PMID 36836780, 2023). "Some of the most well-characterized RTKs implicated in cancer include the “HER family”, i.e., epidermal growth factor receptor (EGFR), ErbB2 (neu, HER2), ErbB3 (HER3) and ErbB4 (HER4), as well as VEGF/VEGFR, which is discussed in the following paragraphs." (PMID 38136430, 2023). "ERBB family fusions involving the EGFR, ERBB2 and ERBB4 genes are emerging therapeutic targets in several cancer types." (PMID 37168365, 2023). "Another up-regulated gene involved in protein phosphorylation and cancer pathways was ERBB4, while EGFR was down-regulated." (PMID 36430510, 2022). "The ErbB oncogenic receptor tyrosine kinase family proteins (ErbB1, ErbB2, ErbB3, and ErbB4) have been shown to contribute significantly to pro-proliferation, migration, invasion, and drug resistance characteristics of diverse cancer cell types." (PMID 35806132, 2022). "These include unique cancer patient samples harboring EGFR E709K (n = 67), EGFR E928K (n = 1), ERBB2 E717K (n = 10), ERBB3 E925K (n = 7), ERBB4 E715K (n = 8), and ERBB4 E934K (n = 5) variants." (PMID 36860695, 2022). "Previous studies have revealed that neuregulin-dependent ErbB3 and ErbB4 signaling in cancer cells contributed to VEGF-mediated angiogenesis and anti-apoptosis." (PMID 35053480, 2022). "ErbB4 nuclear immunoreactivity is also associated with poor patient survival, compared with women whose cancer cells had membranous ErbB4 staining." (PMID 36119496, 2022). "Although all four ERBB receptors were implicated in cancer, only ERBB1, ERBB2, and ERBB4 have intracellular tyrosine kinase domains." (PMID 35765648, 2022). "These two ERBB4 isoforms were selected for the experimentation as they represent the isoforms present in epithelial-derived cancer tissues." (PMID 36860695, 2022). "EGFR family comprises four types of tyrosine kinase receptors, including ErbB1 (HER1), ErbB2 (HER2), ErbB3 (HER3), and ErbB4 (HER4), and it is highly expressed in cancer cells." (PMID 35565451, 2022). "Depletion of AP-1 or GGA2 also reduced cell contents of other tyrosine kinases, MET and ErbB4, and therefore, suppressed the growth of H1975 cancer cells in culture and xenograft model." (PMID 34799560, 2021). "In the present study, we evaluate the prevalence of KDD in ERBB family members (EGFR/EGFR, ERBB2/HER2, ERBB3/HER3, and ERBB4/HER4) across multiple types of human cancers in order to refine our understanding of KDD as an oncogenic driver." (PMID 33654076, 2021). "The prognostic significance of ERBB4 in pan-cancer was analyzed by another cohort from the cBioPortal of Cancer Genomics." (PMID 34620079, 2021). "The epidermal growth factor (EGF) family is closely associated with cancer; HER4 (ErbB4) is expressed in a series of isoforms owing to AS." (PMID 33996533, 2021). "Human epidermal growth factor receptor 4 (HER4/erbB4) regulates growth and differentiation in many cancer types." (PMID 36046141, 2021).
cancer (continued). "Receptor tyrosine kinases (RTK) like the ERBB receptor family, including EGFR/ERBB1, ERBB2/NEU, ERBB3, and ERBB4, are important regulators of skin homeostasis and their dysregulation often results in cancer, which makes them attractive therapeutic targets." (PMID 33786987, 2021). "The cancer-promoting effects of VANGL1 have been associated with influencing the function of KAI1, ErbB4-c-Jun and Dishevelled (Dvl)-PKC signaling." (PMID 33228740, 2020). "The ERBB family of tyrosine kinase receptors, including EGFR (ERBB1/HER1), ERBB2 (Neu/HER2), ERBB3 (HER3), and ERBB4 (or HER4), has largely been associated with cancer pathogenesis and epithelium-mesenchymal transition (EMT)." (PMID 32316671, 2020). "While there was a negligible reduction in the overall mutational load after filtering highly recurrent variants, the filtering impact was notable for several known cancer-related genes (e.g., ERBB4 and MUC16)." (PMID 31262303, 2019). "While the majority of somatic mutations in the EGFR and ErbB2 kinases increase the kinase activity, a number of the classified ErbB4 cancer mutants have been shown to inhibit or reduce the kinase activity." (PMID 31245384, 2019). "NRG1 is a direct transcriptional target gene of NUP98 and functions along with its receptor ERBB4 in various normal and pathological conditions including cardiac development, cancer and neurodegeneration diseases, etc.." (PMID 31396490, 2019). "Previous studies reported that NRG1 exerts its effects in cancers by directly binding to ERBB3 or ERBB4 which heterodimerizes with ERBB2 and the ligand-receptor interaction, causes the phosphorylation of receptors and activation of signaling cascades." (PMID 30486894, 2018). "With regards to signaling and cancer, ERBB4 activates several of the same downstream proteins as EGFR—such as CBL, STAT5, and SHC but also strongly activates PI3K signaling." (PMID 29342193, 2018). "While much information is available about EGFR and HER2 signaling in cancer, less is known about the role of ERBB4." (PMID 29342193, 2018). "The recently developed multi-kinase inhibitor SKLB1206 showed promising results in inhibiting not only EGFR with gefitinib-sensitive and -resistant mutations but also showed considerable inhibition potency against ErbB2 and ErbB4 in cancer cell lines." (PMID 28417948, 2017). "The roles of EGFR and ErbB2 in cancer development are presently well established, whereas data on ErbB3 and ErbB4 are still rather fragmentary." (PMID 28417948, 2017). "Increasing the expression levels of EGFR family proteins, including EGFR, ErbB2, ErbB3, and ErbB4, can promote the growth of cancer cells." (PMID 29164150, 2017). "ErbB3/HER3 is a member of the epidermal growth factor receptor family of receptor tyrosine kinases comprising HER1 (EGFR), HER2 (ErbB2), HER3 (ErbB3) and HER4 (ErbB4) which play an important role in the development and progression of cancer." (PMID 28448604, 2017). "Our findings suggest the possibility of a new anti-cancer treatment strategy using ERBB4-Akt/mTOR inhibitors in CSCNET patients." (PMID 28042953, 2017). "Erb-b2 receptor tyrosine kinase 4 (ERBB4), also termed HER4, is a member of the ERBB family of RTKs, which includes EGFR and HER2, and mutations in this gene have been implicated in some cancers." (PMID 27980689, 2016). "Members of the human epidermal growth factor receptor (HER) family of receptor tyrosine kinases EGFR (HER1, ERBB1), HER2 (ERBB2), HER3 (ERBB3), and HER4 (ERBB4) are therapeutic targets in several cancers." (PMID 27610130, 2016). "MAPKs are the intracellular effectors of ErbB receptors (EGFR, ErbB2, ErbB3 and ErbB4), and hyperactivation of the ERK1/2 MAPK signaling pathway frequently occurs in human cancer and is associated with increased cell survival and proliferation." (PMID 26843616, 2016).
cancer (continued). "Among cancer-associated molecules were ERBB3 that was downregulated and ERBB4 that was upregulated in BRAFwt PTCs." (PMID 25922907, 2015). "As shown in this figure, EGFR and ErbB-3 are primarily expressed in human carcinomas (50% ∼ 70%); ErbB-2 is expressed in 20% ∼ 30% of these carcinomas; and the expression of ErbB-4 occurs only in breast and colon carcinomas." (PMID 25993617, 2015). "ErbB3 and pErbB3 were nearly absent in glandular epithelial cells of colorectal mucosa adjoining cancer tissue.ErbB4 and pErbB4 immunoreactivity was observed in cancer cells in 33 (21%) and 25 (16%) cases, respectively." (PMID 25416285, 2014). "It appears that ErbB4 protein expression is difficult to detect in cultured cancer cell lines although there have been a few reports that ErbB4 can be detected in certain CRC cell lines." (PMID 25416285, 2014). "Accordingly, a group of genes that we identified by ChIP-seq and that responded differentially to GATA3 (for example, BMP2, ERBB4 and KIF16B) are linked to proliferation and maintenance of normal or cancer stem cells." (PMID 25410484, 2014). "ERBB4 encodes an epidermal growth factor RTK subfamily member that regulates several cellular processes and plays an important role in cancer." (PMID 23967248, 2013). "Given that ErbB1 and ErbB4 colocalization within the same neurons, it is likely that ErbB1 competes with NRG/ErbB4 signals, as was suggested in cancer studies." (PMID 23408472, 2013). "A truncated form of the intracellular domain (ICD) of ErbB-4 undergoing γ-secretase-mediated cleavage has been found in the nucleus of cancer cells, whereas ErbB-4 has been detected as a full-length receptor in the nuclei of some normal cells." (PMID 22520625, 2012). "The EGF receptor family consists of four members: ErbB1/EGFR/HER1, ErbB2/HER2/Neu, ErbB3/HER-3 and ErbB4/HER-4 that are important for cancer development." (PMID 23173670, 2012). "The small number of cancer recurrences (n = 3) or deaths (n = 5) during a follow-up period with a median duration of 5 years precluded studying the prognostic value of serum ErbB4." (PMID 22761786, 2012). "Our findings overall have implications for studying and understanding the role of ErbB4 in the pathogenesis of human complex disease including neurodevelopmental disorders and cancer." (PMID 20886074, 2010). "Interestingly, disruption of the NRG1/ERBB4 axis holds therapeutic potential for both cancer and ALS." (PMID 40469844, 2025). "In addition to a well-established but varying role in tissue differentiation and human cancer, ERBB4 is further intriguing because it has been indirectly implicated in aging and longevity." (PMID 37855863, 2024). "As yet, there is no strong evidence that either ERBB4 mutation or overexpression can induce cancer development and/or progression." (PMID 38534733, 2024). "In addition, CDX2-suppressed cancers had a higher prevalence of mutations in several receptor tyrosine kinase genes, including EGFR, ERBB3, ERBB4, RET, and ROS1." (PMID 39452477, 2024). "HER2 is part of the epidermal growth factor receptor (EGFR/Erb) family of tyrosine kinase receptors, which consists of four members-EGFR/HER1/ErbB1, HER2/ErbB2, HER3/ErbB3, and HER4/ErbB4-and is closely related to cell proliferation, differentiation, migration, and cancer development." (PMID 36937848, 2023). "Upon inhibition of ERBB2, they deduce that ERBB4 may take over as the dominant pathway for cancer growth." (PMID 37072406, 2023). "Some upregulated genes, such as ERBB4 and GL1, are also associated with diverse cancers." (PMID 36836780, 2023). "Previous studies 42, 43 have also confirmed the important role of ErbB4 in cancer." (PMID 37928268, 2023). "Indeed, the EGFR and ERBB families (ERBB2, ERBB3 and ERBB4) were also ranked in the top 10 cancer driver targets in the transcriptional networking, suggesting their roles in uPAR-mediated tumorigenesis processes were highly anticipated." (PMID 37895906, 2023).
cancer (continued). "Importantly, homology-directed repair and ERBB4-mediated nuclear signaling were both upregulated in Black samples compared to White samples in four carcinoma types." (PMID 37345032, 2023). "Among them, the role of ERBB4 in cancer remains controversial." (PMID 36185201, 2022). "Additionally, we calculated the frequencies of genes in the three phenotypes, which were reported to be associated with the invasion and progression of cancer, such as SMAD4, APC, and ERBB4." (PMID 35401671, 2022). "Several studies reported that the abnormal expression and activation of ERBB4 could lead to human cancers and the loss of function due to mutations also associated with autosomal-dominant ALS." (PMID 36590916, 2022). "Results of such studies indicate isoform-specific roles of ErbB4 in cancer." (PMID 36119496, 2022). "The overexpression and/or mutations of epidermal growth factor receptor (EGFR) family proteins, i.e., EGFR (HER1), ERBB2, ERBB3 and ERBB4, are often found in multiple types of cancer cells and are considered to be a significant prognostic indicator in the clinical intervention of cancer." (PMID 35163685, 2022). "Despite the relatively high frequency of somatic ERBB4 mutations in various cancer types, only a few activating ERBB4 mutations have been characterized, primarily due to lack of mutational hotspots in the ERBB4 gene." (PMID 36860695, 2022). "Indeed, the analysis of hotspot regions in genes such as ERBB4, AKT1, FGFR2 and MLH1 underline that specific alterations in the primary tumor are extremely important for cancer prognosis prediction." (PMID 36077746, 2022). "Moreover, this study confirmed the absence or the very low expression of ERBB4 in PC cell lines and primary cancer tissue." (PMID 33918389, 2021). "For cancer driver genes, ERBB4 showed significantly lower expression levels in the LS samples." (PMID 34745971, 2021). "In contrast, the role of ERBB4 in cancer is more controversial." (PMID 32316671, 2020). "Besides, the somatic mutations of the organoids were identified and cancer mutant genes in the most relevant BC genes were also found, including ERBB4, HLA-DRB1, PDE4DIP, PTPN22." (PMID 32774159, 2020). "NRGs belong to the large family of EGF ligands, and are implicated in brain development activities by interacting with ErbB and regulating HER2, HER3, and HER4 (ERBB2, ERBB3 and ERBB4, respectively, in mice), all of which have been linked to different types of cancers in the literature." (PMID 32341755, 2020). "ERBB4 is a tyrosine kinase receptor whose activity in cancer is tissue dependent." (PMID 32316671, 2020). "Indeed, NRG-1, PSEN1 and ERBB4 dysfunction have been described as key contributors in the pathogenesis of cancer, cardiovascular disease, and neurological disorders." (PMID 31396490, 2019). "The EGF receptor (EGFR) (or HER) proto-oncogene family consists of four transmembrane tyrosine kinase receptors (i.e., EGFR, ErbB2, ErbB3, and ErbB4) that play a role in cancer pathogenesis and has been described as key therapeutic target in many types of cancer, including ovarian cancer." (PMID 32039018, 2019). "In addition, ERBB4 is the least expressed EGFR member in all cancer cell lines, even though some studies have implied that ERBB4 plays an important role in cancer development." (PMID 29849821, 2018). "Further studies will improve our understanding of how ATRX and ERBB4 mutations and AKT/mTOR signaling promote CSCNET tumorigenesis, and may be leveraged in novel anti-cancer treatment strategies." (PMID 28042953, 2017).